SRPK1 (SRSF protein kinase 1)
Diseases named in the same sentence as SRPK1 in open-access papers (continued):
Sharing a sentence is not in itself a finding about the gene and the disease.
tumor (continued). "However, SRPK1 inhibition or downregulation has also been linked with cis/carboplatin chemotherapy resistance, highlighting that the therapeutic benefit of SRPK inhibition is likely tumour‐type and/or isoform dependent." (PMID 37607329, 2023). "Therefore, SRPK1 was recognized as a potential target for anti-tumor therapies." (PMID 35192432, 2022). "As the major substrates of SRPK1, the expression of SRSFs (serine/arginine-rich splicing factors) were also altered in malignances in accordance with SRPK1, indicating the SRPK1 may modulate tumor progression by modulating the alternative splicing process." (PMID 35192432, 2022). "Therefore, SRPK1 inhibition would require more caution if applied in brain cancers, as it could result in both tumor-suppressive and -promotive effects." (PMID 31861708, 2019). "Furthermore, if indeed the mechanistic differences between tumour types persist as more studies emerge, we may see variation in the clinical role of small‐molecule SRPK1 inhibitors, depending on cancer type." (PMID 27859253, 2017). "Importantly, genetic or pharmacological interference with SRPK1 activity caused a switch in the expression of proangiogenic towards antiangiogenic VEGF splice isoform, resulting in decreased microvessel density and reduced tumour growth." (PMID 26273627, 2015). "Further analysis of TCGA LUAD cohort data revealed that the expression levels of SRPK1, SRSF1, and RBM39 significantly upregulated in tumor compared to adjacent non‐tumor tissues, and positively correlated with RAC1B levels." (PMID 40548642, 2025). "These functional experiments provide strong evidence that BOP1, CTBP1, DSE, PMSD10, and SRPK1 play key roles in LMS progression, acting as potential therapeutic targets to limit tumor invasion and metastasis." (PMID 40963856, 2025). "Functional validation experiments confirmed that BOP1, CTBP1, DSE, PMSD10, and SRPK1 promote LMS cell migration, invasion, and colony formation, further highlighting their role in tumor progression." (PMID 40963856, 2025). "Immunohistochemical experiments detected the expression of SRPK1 downstream, β-catenin, p-JAK-2, and p-STAT3 in subcutaneous tumor tissues of nude mice." (PMID 38397980, 2024). "Taken together, these findings demonstrated that SRPK1 enhanced the Warburg effect by regulating the rate-limiting enzyme PKM1/2 and hence promoting tumour growth in LUAD." (PMID 39095708, 2024). "Knockdown or chemical inhibition of SRPK1 alters splicing from VEGF165 to VEGF165b, thereby inhibiting angiogenesis and tumor progression." (PMID 37342192, 2023). "According to our data, SRPK1 can promote the proliferation, migration, and invasion of CESC, thus promoting tumor progression." (PMID 35192432, 2022). "Meanwhile, small molecules targeting SRPK1 can switch splicing of VEGF mRNA to generate the VEGF165b isoform and decrease tumor growth." (PMID 36140826, 2022). "SPHINX was shown to be more selective but similarly potent for SRPK1 compared to SRIN340, was shown to significantly downregulate VEGF165 expression, and inhibit tumor growth in an orthotopic mouse model of prostate cancer." (PMID 35463320, 2022). "USP39 acted as a pro-tumor factor by motivating the malignant biological processes of RCC, probably through inhibiting VEGF-A165b alternative splicing and regulating SRSF1 and SRPK1." (PMID 34544400, 2021). "For all patients, a fresh tumor biopsy will be obtained prior to treatment and this biopsy will be used for ABCG2 and SRPK-1 staining." (PMID 32708825, 2020). "Our data indicate a further role for WNK1 in the regulation of alternative splicing of tumor-related RAC1B, through complex formation with GSK3β and SRPK1." (PMID 33315986, 2020). "In conclusion, Wt1 activates Srpk1 and Srsf1 and induces expression of angiogenic VEGF isoforms in tumor endothelium." (PMID 30641926, 2019).
tumor (continued). "A supporting set of in vivo experiments on BALB/c nude mice showed that tumours formed by SRPK1‐transduced NSCLC cells were larger than those formed by controls, with the opposite being observed when SRPK1‐silenced cells were inoculated." (PMID 27859253, 2017). "It is well known that SRPIN340 has a higher inhibitory activity over SRPK1 compared to SRPK2, implying that this compound would be less effective against tumor cells with higher SRPK2 expression." (PMID 26244849, 2015). "First, lower level of SRPK1 expression has been shown to correlate with resistance of ovarian, testicular and HT29 tumor cell lines to platinum-containing treatment regimens." (PMID 23236423, 2012). "Taken together, our results indicated that the non-kinase domain of SRPK1, a positive regulator directly affecting Wnt/β-catenin pathway, facilitates the regulation of mEGFR levels and tumor growth under gefitinib treatment in NSCLC." (PMID 36869126, 2023). "SRPK1 silencing did not impact cell proliferation, invasion or migration in vitro, but was shown to stunt tumour growth in vivo in this study." (PMID 35583632, 2022). "On the other hand, SRPK1 genetic targeting did not significantly impair cell proliferation, increased invasion activity, and seemed to apparently increase tumor progression in vivo." (PMID 36212152, 2022). "Abnormal activity of SRPKs, mostly SRPK1 and SRPK2, has been found in different cancer types, where they act in cellular processes related to tumor development and metastasis, such as angiogenesis, epithelial-mesenchymal transition (EMT), and cell migration." (PMID 36212152, 2022). "Consistent with mRNA data, both SRPK1 and SRPK2 proteins were elevated in tumor tissues." (PMID 33602301, 2021). "In most of these cancers, SRPK1‐upregulation was correlated with poor outcome and negative prognostic factors, such as higher tumour grade and stage or metastatic behaviour." (PMID 34092037, 2021). "Besides, both SRPK1 and SRPK2 mRNA levels were upregulated in tumor tissues comparing with adjacent tissues in our primary cohort." (PMID 33602301, 2021). "As SRPK1 and BRD4 proteins are involved in metastasis, SPHINX31 may be used to prevent tumor dissemination." (PMID 31134126, 2019). "SRPK1 has been previously implicated in cancer progression and metastasis through its regulation of VEGF splicing, yet we did not observe an inhibition of primary tumor growth when SRPK1 expression was reduced." (PMID 29904055, 2018). "Knockdown of SRPK1 switched VEGF splicing towards the antiangiogenic isoform in PC3 cells line and decreased tumour growth in xenografts as well as microvessel density in tumours." (PMID 26995304, 2016). "Since regulation of SRSF2 involved acetyltransferase Tip60, and kinases SRPK1 and SRPK2, it is conceivable to speculate that in most tumor cells the regulation of SRSF2 was disturbed." (PMID 22957056, 2012). "Although much evidence has verified the importance of SRPK1 in tumorigenesis, no study to date has revealed the epigenetic regulatory mechanism of aberrant SRPK1 expression and the activity of SRPK1 in the metabolic reprogramming of tumour cells." (PMID 39095708, 2024). "Thus, the upregulation of SRPK1 and SRSF1 activity frequently observed in human cancers might contribute to the ability of the tumour mass to promote neoangiogenesis and redirect the blood stream towards itself." (PMID 26273627, 2015). "The effects of inhibition of SRPK1 and SRPK2 by the compounds may be revealed using in vivo tumor models with WT1 mutations rather than cell culture models." (PMID 25581376, 2015). "Hence, it is conceivable that SRPK1 may be differentially modulated in distinct tumours, and the protein level is not the only determinant for its role in cisplatin responsiveness." (PMID 32461560, 2020).
cancer (71 papers, 2006 to 2026). A tumor composed of atypical neoplastic, often pleomorphic cells that invade other tissues. "Validating our results, the majority of the key signaling SRPK1 amino acids identified in the present study are related to cancer‐associated mutations of the SRPK1 gene, as revealed by screening of a portal for cancer genomics." (PMID 39462863, 2025). "Further validating our findings, the majority of these amino acids are related to cancer‐associated mutations of the SRPK1 gene." (PMID 39462863, 2025). "SRPK1, a protein kinase central to alternative splicing regulation, is implicated in cancer development and progression." (PMID 39083441, 2025). "We also included four additional splicing regulatory genes (HNRNPA2B1, HNRNPH1, HNRNPCL1, and SRPK1) because they are either related to cancer in general or have been associated with telomere biology (HNRNPA2B1:; HNRNPH1:; HNRNPCL1:; SRPK1:)." (PMID 37531400, 2023). "For example, SRPK1, an enzyme that phosphorylates splicing factors rich in serine/arginine domains (SR proteins), is associated with poor survival in various cancers." (PMID 36304306, 2022). "The authors identify that loss of SRPK1 sensitises cancer cells to indisulam treatment and loss of CAND1 confers resistance." (PMID 35534224, 2022). "Taken together, we show that loss of SRPK1 is synthetic lethal with indisulam treatment in multiple cancer cell lines." (PMID 35534224, 2022). "Among them, SRPK1 inhibition caused a cancer‐relevant switch in the pre‐mRNA of the transcriptional regulator BRD4." (PMID 34092037, 2021). "In most cases, the pro‐tumoral activity of SRPK1 was associated with modulation of select splice‐variants in cancer cells." (PMID 34092037, 2021). "They found that SRPK1‐transduced cells expressed higher levels of pluripotency‐associated markers, and showed Hoescht33342 dye exclusion (a marker for cancer stem cells) and greater self‐renewal capacity." (PMID 27859253, 2017). "The ability of Myc to regulate SRSF1 and of WT1 to regulate SRPK1 expression is particularly interesting as these two transcription factors are associated with a wide range of cancers." (PMID 24101931, 2013). "Serine–arginine protein kinase 1 (SRPK1) is associated with the pathogenesis of various cancers." (PMID 39095708, 2024). "SRPK1 is involved in a diverse array of signalling pathways associated with various cancers." (PMID 35583632, 2022). "Furthermore, in some cancers misregulation of SRPK1 has been linked with cell proliferation, migration, and angiogenesis." (PMID 34542927, 2021). "Whether a high level of SRPK1 gene is directly associated with resistance to cDDP treatment in human cancer cells remains controversial." (PMID 23236423, 2012). "Serine-arginine-rich protein kinase 1 (SRPK1), a kinase that specifically regulates the phosphorylation of serine/arginine-rich splicing factors, is markedly overexpressed in various cancers." (PMID 41141389, 2026). "Considering the crucial involvement of SRPK1 in cancer pathogenesis, we further explored its mechanisms." (PMID 41141389, 2026). "In vitro assays were performed to evaluate SRPK1 inhibition and antiproliferative activity in selected cancer cell lines." (PMID 41180468, 2025). "Overactive SRPK1 and SRPK2 are associated with more aggressive cancer and increased drug resistance." (PMID 39083441, 2025). "Its overexpression has been associated with the progression of various malignancies, positioning SRPK1 as a promising target for cancer treatment." (PMID 41180468, 2025). "One such inhibitor is SPHINX31, which has been modified from SRPIN340, which targets SRPK1 and has demonstrated efficacy in inhibiting SRPK1 in various cancer models." (PMID 41551143, 2025). "The SRPK1 pathway plays a critical role in initiating cancer by influencing cell survival mechanisms and promoting aggressive cancer traits." (PMID 39083441, 2025).
cancer (continued). "Several findings presented inhibition of SRPK1 using siRNA, shRNA and specific inhibitors on cell-based effects of cancers." (PMID 41403742, 2025). "Reducing SRPK1 expression can make cancer cells more responsive to chemotherapy and decrease their invasive capabilities, highlighting its potential as a target for new cancer therapies." (PMID 39083441, 2025). "Geo140, the JH-VII-139-1-based hybrid with 5-FU exhibits notable SRPK1 inhibitory potency and cytotoxic effects against HeLa and K562 cancer cells." (PMID 41180468, 2025). "The best studied is the SR-protein kinase SRPK1 which is highly expressed in many tumors such as cancers of breast, pancreas, lung, colon, prostate and gliomas." (PMID 38658776, 2024). "Previous literature has reported that METTL3 is essentially involved in glucose metabolism in various cancers, but the mechanism and function of SRPK1 in glucose metabolism in LUAD remains largely undetermined." (PMID 39095708, 2024). "Silencing of SRPK1 in cancer cells induces altered VEGF splicing to antiangiogenic VEFG165b isoform, enhances apoptosis, and decreases migration and invasion." (PMID 38658776, 2024). "Together, these studies suggest the therapeutic potential of targeting SRPK1 in a variety of cancers, including blood-borne cancers." (PMID 36895328, 2023). "In this work, the synthesis of JH-VII-139-1 peptide conjugates with c(RGDyK) and the properties of the new hybrid compounds against SRPK1, cancer cell growth and angiogenesis are reported." (PMID 36839704, 2023). "The synthesized (JH-VII-139-1)-c(RGDyK) conjugates retained the inhibitory activity of JH-VII-139-1 against SRPK1, while exhibiting different cytotoxicity profile against cancer cells expressing integrins to various extend." (PMID 36839704, 2023). "Aberrant SRPK1 expression can dysregulate SR proteins’ function, resulting in aberrant pre-mRNA splicing, which contributes to cancer progression." (PMID 36140826, 2022). "Reports have shown that elevated levels of SRPK1 expression are associated with risk and prognosis in liver, breast, and lung tumors, while the specific mechanisms of SRPK1 in cancer progression remain to be classified." (PMID 36172261, 2022). "In contrast SRPK1 inhibition alone is sufficient to interfere with AKT signalling in many other cancers." (PMID 35583632, 2022). "It is probable that further studies will reveal miRNA to have a more prominent role in the regulation of SRPK1, with further SRPK1-specific mi-RNA likely to be identified in the context of other cancers." (PMID 35583632, 2022). "Elevated SRPK1 expression correlates with advanced disease stage and poor survival in many epithelial derived cancers." (PMID 35583632, 2022). "One example of this phenomenon is SRPK1 whose overexpression or depletion promotes cancer by inducing Akt activation." (PMID 35986377, 2022). "Here we review SRPK1’s relationship with various cancers by performing a systematic review of all relevant published data." (PMID 35583632, 2022). "As one of the key moderators of AS, it is likely SRPK1 has a role in cancer stem cell isoform selection, this represents a further potentially exciting avenue of research relating to the role of SRPK1 in oncogenesis that remains unexplored." (PMID 35583632, 2022). "For example, overexpression of the SRPK1 protein in cancer cells and its autologous antibody in plasma was observed in patients with acute-type of adult T-cell leukemia." (PMID 36303126, 2022). "Yet, apart from the subcellular localization, the sensitivity of a cancer cell line to cisplatin seems also to be critical in determining the role of SRPK1 in drug responsiveness." (PMID 35719374, 2022). "Up to now, SRPK1 has been extensively studied in tumors, having a prognostic and potential predictive role in various cancers." (PMID 35846993, 2022).
cancer (continued). "Several SRPK1/2-related roles in cancer have been reported, such as angiogenesis, proliferation, cell migration and EMT, metastasis, lipid biosynthesis, genome stability maintenance, and drug resistance mediation." (PMID 36212152, 2022). "The critical role of SRPK1 in malignancies has been reported in several human cancers, including lung, breast, prostate, cervical, colorectal, stomach, and liver cancers." (PMID 36303126, 2022). "And the inhibition of SRPK1 has been demonstrated to attenuate angiogenesis by altering VEGFA-165a to VEGFA-165b in cancer and kidney-related study." (PMID 34544400, 2021). "Two clinical trials testing the efficacy of an SRPK1 inhibitor in human cancer are currently reported as actively recruiting." (PMID 34092037, 2021). "Pharmacological inhibition of SRPK1 activity was shown to exert anti‐angiogenic effects, suggesting the potential value of this approach for anti‐cancer therapies." (PMID 34092037, 2021). "SR proteins are misregulated in multiple cancers, and pharmacological targeting of the SRPK1‐SR axis has been proposed as a potential therapeutic approach." (PMID 34542927, 2021). "SRPK1 expression and/or activity was shown to promote several of the hallmarks of cancer, including proliferation, resistance to apoptosis, migration and angiogenesis." (PMID 34092037, 2021). "SCO‐101 is a drug described as an inhibitor of ATP‐Binding Cassette (ABC) efflux pumps and of SRPK1, which displayed anti‐cancer potential in combination with docetaxel in triple negative breast cancer cells." (PMID 34092037, 2021). "Cancer cells with knockdown of SRPK1 increased the expression of VEGF-A165b and reduced the expression of VEGF-A165." (PMID 34544400, 2021). "Although the aberrant expression of SRPK1 has been recorded in many cancers, including lung, prostate, male germ cells, retinoblastoma, pancreas, colon and breast, the kinase is controversially related to both chemotherapy sensitivity and resistance." (PMID 32461560, 2020). "Inhibiting SRPK1 activity or enhancing its acetylation re-sensitises cells to cisplatin, suggesting a potential strategy to treat cancers resistant to platinum-based therapy." (PMID 32461560, 2020). "In NSCLC, a main oncogenic process affected by SRPK1 was reported to be the acquisition of a CSC (cancer stem cell) phenotype." (PMID 31861708, 2019). "The following review examines the role of SRPK1 as a prognostic factor and potential therapeutic target in cancer and is structured as follows." (PMID 31861708, 2019). "Second, we describe the published preclinical studies (cell lines and/or animal models) that support SRPK1 candidacy as a target for cancer treatment." (PMID 31861708, 2019). "Imbalances in posttranslational modification of SR proteins in cells harboring SRPK1 mutants not only affect splicing efficiency and alternative splicing but is also a disease phenotype in certain cancers and therefore the inhibition of SRPK1 is a drug target." (PMID 31641093, 2019). "Accumulating evidence suggests that serine-arginine protein kinase 1 (SRPK1), an enzyme that phosphorylates splicing factors rich in serine/arginine domains, has a prognostic and potential predictive role in various cancers." (PMID 31861708, 2019). "This chapter mainly focuses on the processes affected in each cancer when SRPK1 is downregulated (e.g., by inhibitors or gene silencing), while it briefly describes the effects of SRPK1 upregulation and the main pathways involved." (PMID 31861708, 2019). "SRPK1 has been investigated in clinical material of various cancers, and its expression has been correlated with prognostic factors (e.g., staging, grading, and molecular subtypes) and survival." (PMID 31861708, 2019). "SRPK1 is also highly expressed in the premalignant changes of some cancers, showing a potential role in the early steps of carcinogenesis." (PMID 31861708, 2019). "Another hit, SRPK1, is a VEGF splice regulator previously linked to cancer progression and metastasis." (PMID 31225451, 2018).